PCYT1B (phosphate cytidylyltransferase 1B, choline)
Description:
[Isoform 1]: Catalyzes the key rate-limiting step in the CDP-choline pathway for phosphatidylcholine biosynthesis. [Isoform 2]: Catalyzes the key rate-limiting step in the CDP-choline pathway for phosphatidylcholine biosynthesis.
Synonyms: CCTB; CCT-beta; CTB; CCTbeta
Tractability: PROTAC: ubiquitination databases record sites on it; its protein half-life has been measured.
Gene: Protein-coding gene on chromosome X (24,558,087 to 24,672,677, reverse strand). Ensembl gene ENSG00000102230.
Subcellular location: Cytoplasm (Isoform 1); Endoplasmic reticulum; Endoplasmic reticulum (Isoform 2)
Pathways (Reactome):
Metabolism: Synthesis of PC
Gene Ontology:
Molecular function: choline-phosphate cytidylyltransferase activity; phosphatidylcholine binding; catalytic activity
Biological process: CDP-choline pathway; phosphatidylcholine biosynthetic process; phosphatidylcholine metabolic process
Cellular component: endoplasmic reticulum; cytoplasm; endoplasmic reticulum membrane
Homologues: Orthologues: chimpanzee PCYT1B (100% identical), macaque PCYT1B (99% identical), pig PCYT1B (99% identical), guinea pig PCYT1B (98% identical), mouse Pcyt1b (98% identical), rabbit PCYT1B (90% identical), rat AABR07038849.1 (89% identical), dog PCYT1B (88% identical), tropical clawed frog pcyt1b (86% identical), zebrafish pcyt1ba (78% identical), zebrafish pcyt1bb (67% identical), Drosophila melanogaster Pcyt1 (47% identical), and 3 more. Paralogues in human: PCYT1A (67% identical), PCYT2 (22% identical).
Diseases named in the same sentence as PCYT1B in open-access papers:
PCYT1B is named in the same sentence as 11 diseases in open-access papers, as found by Europe PMC text mining. Sharing a sentence is not in itself a finding about the gene and the disease. The quoted sentences say what the papers report.
cataract (1 paper, 2025). Partial or complete opacity of the crystalline lens of one or both eyes that decreases visual acuity and eventually results in blindness. "A DT model trained on the in vivo dataset (GSE230320), using the genes PLAGL2, CMTM7, NR1D2, and PCYT1B, not only accurately predicted cataracts in the other in vivo dataset but also demonstrated good predictive performance in two separate ex vivo datasets." (PMID 40027191, 2025). "Only PCYT1B was significantly differentially expressed between the cataract and control groups across analyzed datasets." (PMID 40027191, 2025). "Although one gene (PCYT1B) was found to be significantly different between the two groups in the GSE230322 dataset, the overall gene expression patterns between cataract and control samples were very similar in this dataset, as shown in the heatmap." (PMID 40027191, 2025).
glioblastoma (1 paper, 2023). The most malignant astrocytic tumor (WHO grade IV). "CCTβ/PCYT1B expression has been reported to be lower in glioblastoma and anaplastic astrocytomas than in healthy brain tissue." (PMID 37046844, 2023).
Hepatic steatosis (1 paper, 2024). Steatosis is a term used to denote lipid accumulation within hepatocytes.
hepatocellular carcinoma (1 paper, 2024). A malignant tumor that arises from hepatocytes. "By comparing the expression of PCYT1B in human hepatocellular carcinoma (HCC) of different grades and in normal tissues, we found that expression of this enzyme was significantly high in normal tissues but strongly declined in high-grade tumors, negatively correlating with tumor progression." (PMID 38194288, 2024).
nonalcoholic fatty liver disease (1 paper, 2024).
Obesity (1 paper, 2024). Accumulation of substantial excess body fat. "Gene PCYT1B (phosphate cytidylyltransferase 1B, choline, Q9Y5K3) is involved in lipid metabolism, potentially linking it to obesity or metabolic disorders." (PMID 38666884, 2024).
pancreatic cancer (1 paper, 2014). "The gene PCYT1B in the TGFβ pathway is frequently deregulated in cancer cells compared with normal cells, which might help to grade the stage of pancreatic cancer patients." (PMID 24565114, 2014).
tumor (1 paper, 2024). "Collectively, these findings suggest that PCYT1B is a tumor suppressor whose enzymatic activity is indispensable for its tumor-suppressive capability." (PMID 38194288, 2024). "PCYT1B is a tumor suppressor and metabolic enzyme activity is required for its tumor-suppressive capacity." (PMID 38194288, 2024). "Consistent with this, lower PC levels in the liver of mice with liver-specific knockout of PCYT1B decreased tumor burden, TG levels, and mTORC signaling in the liver, while PC administration abolished these effects." (PMID 38194288, 2024). "We next investigated whether the enzymatic activity of PCYT1B is required for its tumor-suppressive function." (PMID 38194288, 2024). "Moreover, decreased PCYT1B expression was significantly correlated with poor patient survival, suggesting that PCYT1B may play a role in suppressing tumor development." (PMID 38194288, 2024).
PCYT1B also shares sentences with these, for which no sentence is quoted: cancer (1 paper); COVID-19 (1); metabolic disorders (1).